CA9 (carbonic anhydrase 9)
Diseases named in the same sentence as CA9 in open-access papers (continued):
Sharing a sentence is not in itself a finding about the gene and the disease.
tumor (continued). "The expression of CA9 gene was markedly induced under hypoxic conditions in tumor cells and CA 9 may maintain extracellular acidic pH in microenvironment and help cancer cells grow and metastasize." (PMID 24349364, 2013). "In addition to the HIF-1-mediated metabolic reprogramming, HIF-1-dependent expression of carbonic anhydrase 9 (CA9) on the tumor cell surface also contributes to extracellular acidification by hydrating CO2 to HCO3− and H+." (PMID 23203043, 2012). "CA9 is considered to be a surrogate marker of tumor hypoxia." (PMID 22848476, 2012). "Through this activity, CA9 helps maintain a normal pH in tumor cells in a hypoxic microenvironment, which may allow tumor cell proliferation." (PMID 23226559, 2012). "Both, EF5 and CA-9, were assessed separately in the stromal and tumor components of the tumor." (PMID 24213469, 2012). "The hypoxia-associated marker carbonic anhydrase IX (CA9) and double FOXP3/CXCR4 staining were performed on sections from a subset of these cancers including 10 basal-like and 11 luminal cancers matched for tumour grade." (PMID 21521526, 2011). "The percentage of CA9-positive tumour cells was similar to that previously reported and was closely correlated between primary NSCLCs and brain metastases (r=0.825, P=0.0002), suggesting that there were similar levels of hypoxia in matched cases from this series." (PMID 21540863, 2011). "CA9 catalyzes the reversible hydration of carbon dioxide into bicarbonate and protons, thereby contributing to the maintenance of a more alkaline intracellular pH and tumor survival." (PMID 21455298, 2011). "In addition to microarray analysis, quantification of the tumor hypoxia regulated genes CA9 and LOX was performed with real time PCR." (PMID 21477371, 2011). "The necrotic regions in the OCUM-12 tumours corresponded with HIF-1α or CA9-positive regions." (PMID 20145613, 2010). "Carbonic anhydrase 9 (CA9) is one of the representative markers for tumor hypoxia; it is a transmembrane protein that plays a major role in the adaptation and proliferation of cells, in hypoxic and acidic conditions, by regulating the intracellular and extracellular pH." (PMID 19619339, 2009). "CA9, a transmembrane protein, converts carbon dioxide to bicarbonate and hydrogen, and thus regulates the microenvironment pH, as well as influences other processes such as cell-cell adhesion, proliferation, and invasion of tumor cells." (PMID 19619339, 2009). "Therefore, to improve the results of cancer therapy, it is important to control CA9, which is induced under hypoxic conditions and acidifies the tumour milieu." (PMID 18841153, 2008). "As a tumour grows in size, its centre gradually becomes starved of oxygen, and high expression of CA9 might therefore indicate that a tumour has a greater propensity for enlargement." (PMID 18841153, 2008). "In the tumour centre, 76 (59.8%) of the 127 primary tumour specimens showed CA9 positivity." (PMID 18841153, 2008). "In the tumour surface, 39 (32.2%) of the 121 primary tumour specimens showed CA9 positivity, whereas in the tumour-invasive front, 28 (22.4%) of 125 primary tumour specimens showed CA9 positivity." (PMID 18841153, 2008). "CA9 is a marker of hypoxia, and its expression is significantly correlated with tumour size." (PMID 18841153, 2008). "Although many studies have concluded a low tumor pO2 is associated with CA9 expression, other studies point out the lack of direct correlation between CA9 expression and pO2." (PMID 19057672, 2008). "Here we describe an alternative splicing variant of the CA9 mRNA, which does not contain exons 8–9 and is expressed in tumour cells independently of hypoxia." (PMID 18026188, 2008). "CA9 expression, an intrinsic cellular marker for hypoxia, has been suggested to correlate with poor survival in high-grade STS, and GLUT1 expression and enhanced glucose metabolism in STS have been linked to proliferative activity and tumor grade." (PMID 17359542, 2007).
tumor (continued). "This neoplastic cell localization was significantly associated with the phenotype of the tumour – with nuclear and cytoplasmic location being positively correlated with low and high tumour grade, respectively, and cytoplasmic FIH-1 also being associated with CA9 expression." (PMID 18096060, 2007). "CA9 and Hif-1α expression were correlated (primary tumours P=0.005; lymph node metastases P<0.001)." (PMID 16251878, 2005). "Therefore, high CA9 expression indicates severe tumor hypoxia and high tumor stemness." (PMID 40873634, 2025). "EMT also seems to be linked with the function of miR-205-5p, while miR-210-3p seems to inhibit the tumor growth and metastasis of BC via targeting fibroblast growth factor receptor-like 1 and is also strongly associated with markers of tumor hypoxia like HIF-1α, CA9, Glut-1 protein." (PMID 35365098, 2022). "The association of G-CSF with poor prognosis in these tumours may be related to a predominant acidotic microenvironment due to constitutive activation of hypoxia-inducible factor 1-α and upregulation of CA9, which encodes CAIX." (PMID 33804486, 2021). "Therefore, our research suggested that CA9 could be used as a potential predictor of tumour grade and prognosis in TSCC." (PMID 32299152, 2020). "This suggests that CA9 might play a functional role in tumor progression." (PMID 31936274, 2020). "In addition, the reactions to hypoxic tumor environment between EGFR and CA9 are contrary, which may contribute to the tumor progression." (PMID 32365566, 2020). "The release is partially an active metalloprotease-mediated process, that is regulated by different signals and may therefore participate in adaptive changes in the protein composition of tumor cells and of their microenvironment, however, only 10–20% of soluble CA9 is produced by this mechanism." (PMID 30011326, 2018). "However, CA9 expression in the co-culture spheroids grown in the presence of CAFs was not significantly different between 10.05 and Pa03C cultures, indicating that co-culture conditions promote hypoxia signaling, and therefore CA9 expression, similarly in both tumor cell types." (PMID 30214007, 2018). "Moreover, the increased CA9 expression in tumor +CAF co-cultures vs. tumor-only 3D cultures indicates that the CAF cells are likely contributing to an increase in the size of the spheroids and further signaling complexity that lead to increased hypoxia signaling in the tumor cells." (PMID 30214007, 2018). "In addition, a striking increase of CA12 expression was observed in NHE1/CA9-dko tumor extracts." (PMID 28055960, 2017). "Our results support the concept that CA9/hypoxia plays a role in the stem cell niche, and that their targeting in cervix patients with high levels of hypoxia could be beneficial to eradicate tumor growth and reduce recurrence." (PMID 27901496, 2017). "Furthermore, we observed that CA2 was increased in CA9-ko and NHE1/CA9-dko tumor extracts." (PMID 28055960, 2017). "CA9 may be considered to be as a biomarker for hypoxic CRC tumor diagnosis." (PMID 26447758, 2015). "Moreover, CA9 also exhibited strong staining within the tumor tissues." (PMID 26447758, 2015). "Because CA9 maintains intracellular pH and helps tumor cells survive in hypoxic-acidic environments, CA9 may not be directly associated with cyclin E, which helps regulate the cell cycle." (PMID 26156831, 2015). "As CA9 FL was not expressed or expressed in very low amounts in normal kidneys, our study also indicates that it is a tumour-associated gene, which is an important finding because the other genes detected in WTs and nephrogenic rests are usually expressed during organogenesis." (PMID 21910893, 2011). "Therefore, CA9 is frequently used as an “endogenous” marker for low tumor pO2 – bona fide hypoxia." (PMID 19057672, 2008).
tumor (continued). "Thus, either the reversed correlation between CA9 and ER status, or its positive correlation with Her2/neu, could explain the endocrine therapy resistance in tumours expressing high levels of CA9." (PMID 12865916, 2003). "All PDGCAs expressed markers of tumor epithelial and stem cells (EPCAM, CDH1, KRT18, CA9, CD24, CD133), stromal and extracellular matrix components (COL3A1, COL5A1, DCN, PDGFRA, and PDGFRB), and mesenchymal stem cells (CD73, CD105, CD90)." (PMID 40723172, 2025). "The immunohistochemical results showed that the tumor was positive for PAX8, CA9 (diffuse box-like positivity), CK7, CD10, P504S, and vimentin." (PMID 41306531, 2025). "The tumor cells showed expression of PAX8, CA9, AMACR/P504S, Vimentin, CK7, CD10, FH, INI1(SMARCB1) and ELOC(TCEB1), and ELOC was mainly located in the nucleus." (PMID 41306531, 2025). "Transcriptomic profiling revealed that PDGCOs_1 expressed elevated levels of tumor epithelial and stem cell markers, such as EPCAM, CDH1, ALDH3A1, CA9, CD24, and CD133." (PMID 40723172, 2025). "VIRMA upregulated CA9 expression in an m6A-dependent manner in OSCC, and inhibition of VIRMA suppressed tumor growth both in vitro and in vivo." (PMID 40723784, 2025). "To examine the underlying mechanism of pHi decrease, we also tested mRNA expressions of pH‐regulatory genes (CA9, MCT4, NHE1, NBC, and V‐ATPase) in tumor tissues." (PMID 40873634, 2025). "Immunostaining of the tumor showed hepatocyte, arginase 1, Melan-A, HMB-45, CK20, PAX8, CD10, CA9, and TFE3 negativity, as well as AE1/AE3 and CK7 positivity, leading to the diagnosis of clear cell carcinoma of the liver." (PMID 41018392, 2025). "Carbonic anhydrase-9 protein (CA9) is a glycoprotein involved in pH regulation, and it is a biomarker for tumor hypoxia." (PMID 39858084, 2025). "Specifically, HIF-1/2α promotes glucose uptake in tumor cells, acidification of the tumor environment, and the formation of new blood vessels by upregulating genes such as GLUT1, CA9, and VEGF, and supports tumor growth." (PMID 41555916, 2025). "In tongue squamous carcinoma, a hypoxia-associated lncRNA, LINC00887, generates two variants (namely 887S and 887L) that share the same downstream target, Carbonic Anhydrase IX (CA9), a well-known hypoxia-induced gene during tumor progression." (PMID 39714178, 2025). "In summary, ICT appears to function through a dual regulatory strategy: “suppressing malignancy” by downregulating pro-oncogenic genes (CA9, UCK2, and FABP5), and “reinforcing physiological function” by upregulating the potential tumor suppressor CYP2C9." (PMID 41357200, 2025). "Additional mechanisms of progression include tumor hypoxia and overexpression of HIF-1α, CA9, and VEGF, which increase tumor aggressiveness." (PMID 40805266, 2025). "Unpaired and paired differential expression analysis results showed that CA9 and SPINK6 have higher expression in tumor tissue (P < 0.05), indicating their involvement in development of OSCC." (PMID 40703658, 2025). "A similar pattern of gene expression persisted, where CA9 and VEGFA were upregulated within the in vivo RCC243 tumor models and ccRCC patient datasets, whereas FN1 was upregulated within cells grown in the in vitro RCC243 cell culture model." (PMID 40241258, 2025). "CA9, CYFIP2, and LGALS3BP levels were found to significantly increase as tumour grade increased (p < 0.05)." (PMID 38473425, 2024). "In summary, our findings demonstrate that mRNA levels of HIF1A and hypoxia-related genes (CA9, VEGF, GLUT1) are increased in the tumor tissues of HNSCC patients compared to normal tissues." (PMID 38928200, 2024). "Specifically, high levels of miR-210-3p were found to be accompanied by high levels of VEGF and CA9, while the transcription of VEGF and CA9 was found to be mediated by HIF-1α, implying high correlation of miRNAs to the hypoxia within the GBM tumor." (PMID 39055895, 2024).
tumor (continued). "We assessed the hypoxia-related gene expression (HIF1A, EGLN1-3, CA9, GLUT1, VEGF) by qPCR in our study group of 96 tumor tissues and 96 adjacent normal tissues of HNSCC patients." (PMID 38928200, 2024). "HIF-1α also regulates genes involved in cell survival and metabolism, such as phosphoglycerate kinase (PGK), carbonic anhydrase 9 (CA9), Bcl-2 interacting protein 3 (BNIP3), and glucose transporter 1 (GLUT1), all of which contribute to tumor progression." (PMID 38339244, 2024). "For instance, hypoxia upregulates the expression of carbonic anhydrase 9 (CA9), contributing to pH regulation in the tumor microenvironment." (PMID 38732975, 2024). "To confirm the influence on tumor hypoxia, we immunofluorescently labeled mouse tumor tissues using CA9 (Carbonic Anhydrase 9), which is considered an indicator of hypoxia." (PMID 39075504, 2024). "The expression of CA9a hypoxia-inducible factor-1 (HIF-1) target gene, carbonic anhydrase IX (CA9), which is a marker of tumor and poor survival—was also reduced at mRNA and protein levels." (PMID 38786018, 2024). "Carbonic Anhydrase IX (CA9), an enzyme regulated by HIF1α, facilitates the maintenance of pH balance in hypoxic tumor cells, thereby enhancing cell survival." (PMID 39635662, 2024). "CA9 is regulated by the transcription factor hypoxia‐inducible factor‐1α (HIF‐1α), which can regulate the pH value inside and outside of tumor cells and indicate the progression of malignant tumors." (PMID 36537608, 2023). "In contrast, endogenous biomarkers CA9 and 5xHRE/GFP provide direct measurements of the cellular transcriptional response to hypoxia, and we have shown in vitro that tumor cell GFP expression responds dynamically to changing oxygen conditions." (PMID 37285434, 2023). "The results of western blotting and IHC were consistent, in which IGFL2‐AS1 knockdown in nude mouse tumor tissues reduced the HIF‐1α and CA9 expression, whereas IGFL2‐AS1 overexpression had the opposite results." (PMID 36537608, 2023). "Based on a combination of in vitro and in vivo studies, we found that the CA9-BPS-Cu(ii) system is effective at depleting CSCs in high CA9 breast cancer cells and retarding tumour growth under conditions of combined PDT and CDT." (PMID 36819853, 2023). "CA9+ MEC cells were the most abundant cell population in the necrosis regions (36.6%) and were also enriched in the tumor regions on the borders of necrosis." (PMID 37694144, 2023). "To investigate CA9/CA12 expression depending on the molecular subtype, we employed the same CRC datasets and applied the CMScaller to classify tumor samples according to the CMS classification system." (PMID 36982873, 2023). "To validate the expression of 5xHRE/GFP as a marker of BxPC3 tumor cell hypoxia in vivo, we performed immunofluorescence staining on 10 individual BxPC3 tumor samples to correlate GFP expression with conventional markers of tumor hypoxia (i.e., PIMO and CA9)." (PMID 37285434, 2023). "To this end, we used Cancertool to investigate gene expression of CA9 and CA12 in patient tumor samples." (PMID 36982873, 2023). "An examination of core and invasive edges of invasive ductal breast carcinoma showed that tumor edges are characterized by increased staining of HIF-1α, CA9, and GLUT1." (PMID 37490147, 2023). "In human PDAC, both the αSMA+ pericyte coverage and CA9+ hypoxic area were significantly higher in stage-III than stage-I tumors, suggesting progressive deterioration of tumor vasculature over time." (PMID 35626052, 2022). "Immunohistochemical analysis of tumor tissues showed that cold exposure reduced the expression of the proliferative marker Ki-67 and the hypoxic marker carbonic anhydrase 9, and the density of CD31+ tumor microvessels." (PMID 39872073, 2022).
tumor (continued). "HIF-1-driven CA9 expression acidifies the extracellular environment, which in turn activates CAFs to produce MMP2 and MMP9 for ECM breakdown and tumor cell invasion in prostate cancer." (PMID 35884382, 2022). "Altogether, these data strongly confirmed that CA9 DATE can potently activate T cells and redirect them to tumor cells triggering robust tumor cell death." (PMID 35874663, 2022). "Treatment with the CA9 DATE and T cells significantly reduced tumor growth upon completion of the treatment regimen, whereas tumor growth was unaffected in mice receiving the control DATE and T cells." (PMID 35874663, 2022). "The transmembrane isozymes CA9 and CA12 are overexpressed in many tumor types and their overexpression is correlated with poor prognosis in high-grade gliomas." (PMID 36672576, 2022). "CA9 is a cell surface metalloenzyme which catalyzes the reversible hydration of CO2 to produce protons (H+) and bicarbonate (HCO3-), permitting tumor cells to survive exposure to acidosis." (PMID 35874663, 2022). "The main mechanism of action for the CA9 DATE upon binding to T cells and tumor cells is T cell activation and subsequent tumor cell lysis." (PMID 35874663, 2022). "Tumor cells at the outer part of the “pseudo-papillary” structure were CA9-positive (CA9+)/HIF-1α+, whereas cells at the inner part of this structure were CA9−/HIF-1α+ and nestin+/FOXM1+." (PMID 35785200, 2022). "Again, the CA9 DATE and T cell regimen led to a significant reduction in BT241 tumor growth upon completion of the treatment regimen." (PMID 35874663, 2022). "Like CA9, NHE1 is also known to regulate pHi and pHe in tumor cells and is thought to promote tumor cell migration by acidifying their periphery." (PMID 36380966, 2022). "Single-cell classification was applied in tandem with a new method for DCIS ductal segmentation in dual-stained CA9 and FOXP3, whole-tumor section digital pathology images." (PMID 36109587, 2022). "Mice treated with CA9 DATE and T cells had significantly reduced tumor growth which translated to a significant survival benefit over the control arm." (PMID 35874663, 2022). "Upon confirming the antigen specificity of the CA9 DATE for both T cells and tumor cells, we aimed to assess the efficacy of the CA9 DATE by further investigating its ability to activate and re-direct human T-cells against antigen-expressing tumor cells." (PMID 35874663, 2022). "Except for lactic acid, carbonic anhydrase 9 (CA-9), maintaining the acidic condition of TME, also contributed to the tumor progression." (PMID 34178639, 2021). "Compared with those in the normal pancreas (GTEx + TCGA), CA9, TNNT1, CCL21, LY86, and CCL19 were all expressed higher in tumor tissues, except for FABP4, which was expressed lower in a tumor (p < 0.001)." (PMID 34777388, 2021). "The first group included CA9, NDUFA4L2, EGLN3, BHLHE41, VWF, IGFBP3, and ANGPTL4, whose expression levels were coordinately decreased during tumor progression." (PMID 34046336, 2021). "Combined administration of the CA9 inhibitor SLC-0111 and gemcitabine significantly slows tumor growth in multiple PC models." (PMID 33436044, 2021). "In the current study, we investigated the clinical significance of tumor expressions of HIF1A, VEGFA, CA9, and SLC2A1 assessed by IHC and markers of systemic inflammation (NLR and CRP) in pediatric patients with MPNST." (PMID 33810575, 2021). "Overexpression of CA9 in CRC was proven to be correlated with perineural invasion, which was a sign of tumor metastasis and invasion as well as an indication of poor outcome in CRC." (PMID 32630086, 2020). "In response to hypoxia, pancreatic cancer cells, that express activated KRAS, increase the expression of CA9 by stabilizing the transcription factor HIF1A and HIF2A, and mediate pH and glycolysis in the tumour microenvironment." (PMID 32299152, 2020).